MYD88 (MYD88 innate immune signal transduction adaptor)
Diseases named in the same sentence as MYD88 in open-access papers (continued):
Sharing a sentence is not in itself a finding about the gene and the disease.
Arrhythmia (2 papers, 2020 to 2022). Any cardiac rhythm other than the normal sinus rhythm. "The levels of TLR4 and MyD88 and the nuclear translocation of NF‐kB within the PVN were increased after MI, while sympathetic activation and arrhythmia scores were increased and cardiac function was decreased." (PMID 35393774, 2022). "In conclusion, the present study provided novel insights that SSYX may exert anti-arrhythmia effect via increased Ito, ICa-L, and Cx43 expression through regulating TLR4/MyD88/CaMKII signaling pathway, which may be the mechanism of electrical remodeling MetS-induced VA." (PMID 32733242, 2020).
autism (2 papers, 2023 to 2025). Persistent deficits in social interaction and communication and interaction as well as a markedly restricted repertoire of activity and interest as well as repetitive patterns of behavior. "One study using an autism mouse model found that increased gut permeability enabled LPS to reach the brain, triggering the TLR4/MyD88/NF-κB pathway and creating a pro-inflammatory environment." (PMID 40650125, 2025).
autoimmune uveitis (2 papers, 2010 to 2024). An autoimmune form of uveitis (disease). "In other experiments, it has been shown that Gal-3 promotes inflammation through the TLR4 (toll-like receptor 4)/MyD88 (myeloid differentiation primary response 88)/NF-κB (nuclear factor kappa B) pathway in microglia and in animal models of experimental autoimmune uveitis." (PMID 39125698, 2024).
bladder tumors (2 papers, 2024 to 2025). "In conclusion, the finding that Myd88KO mice have changed microbiota and less invasive bladder tumors underscores the importance of both the microbiota and the MyD88 signaling pathway in the development of BC." (PMID 39000291, 2024). "Less invasive bladder tumors in mice lacking functional MyD88 signaling are the major finding of our study." (PMID 39000291, 2024).
bone lymphoma (2 papers, 2017 to 2022). "Targetable alterations are scarce in bone lymphoma; however, in contrast to previous publications, we identified one case with a MYD88 and one case with a CD79B mutation." (PMID 36051079, 2022).
brain inflammation (2 papers, 2018 to 2024). "In both Naglu/Tlr4 and Naglu/Myd88 double-knockout mice, the onset of brain inflammation was delayed for several months when compared with MPS IIIB mice." (PMID 39497064, 2024). "In accordance with our results, it was described in the literature that MyD88/TLR2 signaling regulated infiltration of the peripheral immune cells populations and microglial expansion in response to the acute brain inflammation." (PMID 29719536, 2018).
Breast Tumor (2 papers, 2021). "Concurrent downregulation of several TLR genes and upregulation of downstream genes such as MYD88 in breast tumor versus non-tumor tissues may signify negative regulatory feedback subsequent to stimulation by tumor-associated microbial products." (PMID 33863341, 2021).
bronchiolitis (2 papers, 2008 to 2019). Inflammation of the bronchioles characterized by swelling of the bronchioles and mucus accumulation. "At 4 dpi, MyD88−/− mice continued to exhibit a denuding bronchiolitis, epithelial/endothelial atypia, and the added phenotype of PBV edema without immune cell infiltration around the airway though perivascular infiltration of immune cells was observed." (PMID 19079579, 2008). "Furthermore, infected CCR deficient mice suffered from severe lung pathology (denuding bronchiolitis, epithelial apoptosis, etc.)and defects in inflammatory cell recruitment to the airway that were very similar to those seen in MyD88−/− mice." (PMID 19079579, 2008). "In contrast, WT mice at 2 dpi exhibited pronounced lung inflammation characterized by perivascular cuffing, endothelial and epithelial atypia, and peribronchivascular immune cell infiltration, without the severe denuding bronchiolitis seen in MyD88−/− mice." (PMID 19079579, 2008).
bronchopneumonia (2 papers, 2015 to 2019). Acute inflammation of the walls of the terminal bronchioles that spreads into the peribronchial alveoli and alveolar ducts. "Therapeutic inhibition of the early MyD88 inflammatory response or its resulting damage to lung tissue would be expected to prevent development of bronchopneumonia." (PMID 30642901, 2019). "Although inflammatory foci in MyD88(−/−) lung sections were not as widespread as in control mice, the foci were admixed with cellular debris indicative of severe tissue necrosis, consistent with the development of necrotizing fungal bronchopneumonia." (PMID 25621893, 2015).
Buerger disease (2 papers, 2016 to 2019). "Regarding the MyD88 gene, a single nucleotide polymorphism (SNP) in its 3′-untranslated region (3′-UTR) has been reported to be associated with Buerger disease but not with Takayasu arteritis in the Japanese population." (PMID 26959040, 2016).
Chagas disease (2 papers, 2018 to 2021). A parasitic infection caused by Trypanosoma cruzi. "According to these known information, DEGs (CASP2, CASP8, NOD1, MYD88, TLRs, IL-1s, NAIPs) involved in Chagas disease here are screened, which have been proven to be correlated with the activation or inhibition of multiple Chagas disease related pathways." (PMID 34171992, 2021). "We identified the candidate genes and pathways related to Chagas disease for resisting T. cruzi, it is found that CASP2, CASP8, NOD1, MYD88, TLRs, IL-1s, NAIPs, etc, would be responsible for the T. cruzi infection." (PMID 34171992, 2021).
channelopathy (2 papers, 2023 to 2025). Channelopathies are a group of diseases caused by the dysfunction of ion channel subunits or their interacting proteins. "Accordingly, Piezo2 channelopathy, which has been suggested to be associated with IL-6 increases through the Hsp70/TLR4/Myd88/IL-6 pathway, as in DOMS, could lead to an imbalanced ratio of Th17/Treg in RA, therefore paving the way to the autoimmune response." (PMID 37108693, 2023). "However, when Piezo2 channelopathy may become irreversible in ALS, the activated NF-κB pathway by TLR4/Myd88 signaling keeps on propelling the neuroinflammation in the CNS with non-resolving progressive impairment of the proprioceptive circuitry." (PMID 41155507, 2025).
Chlamydial infection (2 papers, 2015 to 2017). "Because the investigators in those studies demonstrated such a high dependence on STING during chlamydial induction of IFN-β, it was concluded that TLR signaling, MyD88, and TRIF were all dispensable for IFN-β upregulation during chlamydial infection of peritoneal macrophages." (PMID 25798928, 2015).
cold agglutinin disease (2 papers, 2021 to 2023). Cold agglutinin disease is a type of autoimmune hemolytic anemia defined by the presence of cold autoantibodies (autoantibodies which are active at temperatures below 30B0C). "In cases where cryoglobulins and coexisting cold agglutinin disease (CAD) were present, the molecular characteristics were consistent with a CAD clone, with wild-type MYD88 observed in 80% of cases." (PMID 38132918, 2023).
complement deficiencies (2 papers, 2024 to 2025). "The most common defects include antibody and complement deficiencies, congenital asplenia, or innate immune signaling disorders involving MYD88 and IRAK4." (PMID 41510457, 2025).
Cryptosporidium infection (2 papers, 2021 to 2024). "We and other laboratories previously demonstrated activation of the TLR/MyD88/NF-κB signal pathway in intestinal epithelium following Cryptosporidium infection." (PMID 33445463, 2021).
Cyclic neutropenia (2 papers, 2016 to 2020). "Previous case reports describing P. aeruginosa sepsis in children with known PIDs, such as Wiskott–Aldrich syndrome, X-linked agammaglobulinemia, cyclic neutropenia, and IRAK-4/MyD-88 deficiency, were based on conventional, candidate–gene-driven immunological testing." (PMID 27703454, 2016).
demyelination (2 papers, 2020 to 2023). "In conclusion, our findings for the first time indicate that Tregs alleviate myelin loss and improve cognitive function by inhibiting pyroptosis in microglia via TLR4/MyD88/NF-κB pathway in LPC-induced demyelination." (PMID 36803990, 2023). "LQ also decreased the number of MAC-3- and CD45-positive microglia cells in cuprizone mice, EAE mice and mouse TLR4-knockout and myeloid differentiation primary response 88 (MyD88)-knockout demyelination models." (PMID 32545828, 2020). "The expression of these pro-inflammatory cytokines was diminished by LQ via its inhibitory effect on NFκB activation in primary astrocyte cultures from TRL4-, MyD88- or Toll-like receptor adaptor molecule 1 (TRIF)-knockout demyelination mice and cuprizone-fed mice." (PMID 32545828, 2020).
diabetic neuropathy (2 papers, 2018 to 2025). A chronic, pathological complication associated with diabetes mellitus, where nerve damages are incurred due to diabetic microvascular injury involving small blood vessels that supply these nerves, resulting in peripheral and/or autonomic nerve dysfunction. "In this study, we found the interaction between GABAB receptors and TLR4/Myd88/NF-κB pathwaysin the spinal cord in diabetes neuropathy." (PMID 30647535, 2018). "In a study, apigenin ameliorated diabetic neuropathy in rats by modulating the TLR4/MyD88 signalling pathway, which showed inhibited elevated plasma glucose levels, TNF-α, ILs, TLR4, and MyD88 expressions, thus ameliorating STZ (Streptozotocin) -induced allodynia and hyperalgesia." (PMID 40205269, 2025). "Collectively, these findings suggest the interaction between TLR4/MyD88/NF-κB signaling pathways and CXCR4 plays an important role in the diabetic neuropathy." (PMID 30647535, 2018).
disseminated candidiasis (2 papers, 2015 to 2019). Systemic candidiasis occurs when Candida yeast enters the bloodstream and may spread (becoming disseminated candidiasis) to other organs, including the central nervous system, kidneys, liver, bones, muscles, joints, spleen, or eyes. "The importance of TLR-mediated fungal recognition in host defense is supported by the susceptibility to disseminated candidiasis of MyD88-deficient mice." (PMID 31671151, 2019).
duodenal ulcer (2 papers, 2021 to 2024). An ulcer in the duodenal wall. "Expression of TLR4 and MyD88 was significantly reduced in the electroacupuncture group compared with the omeprazole group, indicating that the preventive effect of electroacupuncture on stress ulcers may be exerted specifically via suppression of the TLR4/NF-κB signaling pathway." (PMID 33628315, 2021). "Electroacupuncture and omeprazole may prevent stress ulcers through a combination of antioxidant and anti-inflammatory actions, and by inhibition of the TLR4/MyD88/NF-κB signaling pathway." (PMID 33628315, 2021).
embryonal carcinoma (2 papers, 2014 to 2025). A non-seminomatous malignant germ cell tumor characterized by the presence of large germ cells with abundant cytoplasm resembling epithelial cells, geographic necrosis, high mitotic activity, and pseudoglandular and pseudopapillary structures formation. "This suggests that, similar to EOC, miR-146a is inversely linked to MyD88 in differentiated embryonal carcinoma cancer stem cells." (PMID 24977712, 2014). "Expression of TLR4 and MyD88 was assessed immunohistochemically in 198 paraffin-embedded ovarian tissues and in an embryonal carcinoma model of cancer stemness." (PMID 24977712, 2014). "MyD88 expression was down-regulated in differentiated embryonal carcinoma (NTera2) cells, supporting the MyD88+ cancer stem cell hypothesis." (PMID 24977712, 2014). "Furthermore the changes observed in MyD88 expression in embryonal carcinoma (EC) cancer stem cells, one of the best characterized CSC models in use today, also suggest that MyD88 positive cancer cells are more biologically aggressive than MyD88 negative cells." (PMID 24977712, 2014). "A negative correlation between tumor differentiation and MyD88 expression level was observed in embryonic carcinoma (EOC), indicating that MyD88-positive cancer cells were more aggressive with higher adverse biological characteristics, such as resistance to standard platinum and taxane chemotherapy." (PMID 40404908, 2025).
encephalomyelitis (2 papers, 2025 to 2026). Inflammation of the brain and the spinal cord. "2D2TgDcir -/- Myd88 -/- mice negated the spontaneous development of EAE-like encephalomyelitis." (PMID 42256301, 2026).
endophthalmitis (2 papers, 2023 to 2024). An infectious process affecting the internal structures of the eye. "Gram-positive bacteria activate MyD88-NF-κB signaling mainly through TLR2 in endophthalmitis and G- can activate innate immunity through both the classical MyD88 and non-myd88 pathway." (PMID 39076973, 2024). "We have previously reported that during endophthalmitis progression, Bc stimulates activation of both TLR2 and TLR4 pathways, resulting in signal cascade initiation through both MyD88-dependent and MyD88-independent (TRIF-dependent) pathways, respectively." (PMID 38106476, 2023).
enteropathy (2 papers, 2013 to 2025). "S. TminvG requires CD11c+CX3CR1+ monocytic phagocytes for traversing the epithelial barrier, grows within the LP and elicits enteropathy in a Myd88-dependent fashion by day 3 p.i. in wild type mice." (PMID 24143212, 2013). "However, S.Tmavir did not colonize the LP of MyD88−/− or IFNγ-R−/− mice and did not cause enteropathy (this work and data not shown)." (PMID 24143212, 2013). "Consistent with our previous results, a rat model of diclofenac-induced enteropathy revealed that S. boulardii CNCM I-745 prevented TLR2/4, MYD88, and NF-κB p65 overexpression, thereby decreasing proinflammatory cytokines, such as IL-1β." (PMID 40872558, 2025).
epithelial dysplasia (2 papers, 2014 to 2023). "These published studies revealed no significant changes to cells in the BAL but with significant histopathologic changes in the Myd88-deficient mice, including immune cell entrapment and epithelial dysplasia." (PMID 37108233, 2023). "MyD88 KO mice repetitively exposed to DE exhibited significantly reduced chemokine and cytokine release, dampened BAL cell influx, and epithelial dysplasia." (PMID 37108233, 2023). "Though not as pathological a phenotype as in the MyD88 KO, this reduced Md2 and Irf7 expression could contribute to MyD88-dependent dampened BAL infiltration and epithelial dysplasia in the Ffar4-null mice from our studies." (PMID 37108233, 2023).
Familial adenomatous polyposis (2 papers, 2009 to 2017). Familial adenomatous polyposis (FAP) is characterized by the development of hundreds to thousands of adenomas in the rectum and colon during the second decade of life. "Rakoff-Nahoum and co-workers showed that MyD88 signaling contributes to tumor progression in the ApcMin model of human familial adenomatous polyposis, suggesting a role for intestinal microorganisms in the process of tumorigensis." (PMID 19551144, 2009). "Multiple intestinal neoplasia mice with a point mutation in Apc (ApcMin/+) mimic sporadic cancer and familial adenomatous polyposis, and have been used to study the role of TLR signaling in intestinal tumorigenesis through the crossing with MyD88-deficient mice (MYD88-deficient × ApcMin/+)." (PMID 29354132, 2017).
Fever (2 papers, 2017 to 2022). Body temperature elevated above the normal range. "Exogenous pathogens activate the TLRs signaling pathway constituents such as TLR4, MyD88, TBK1, IRF3, and IRAK4, and subsequently stimulate the release of pro-inflammatory cytokines which promote to progress a disease by producing fever and tissue damage." (PMID 28489052, 2017).
fibroids (2 papers, 2024 to 2025). "A study reported that the TLR4/MyD88/NFKB signaling pathway in primary cultured human fibroblasts from leiomyomas was activated under E. coli LPS treatment, which suggested that bacteria may be involved in the pathogenesis of leiomyomas by inducing cell proliferation through inflammation." (PMID 40041148, 2025). "There is only one report indicating activation of NF-kB and TLR4 in fibroid cells and uterine fibroid-derived fibroblast, and no published reports on MyD88 in fibroids." (PMID 38994944, 2024).
fibromyalgia (2 papers, 2025). A chronic disorder of unknown etiology characterized by pain, stiffness, and tenderness in the muscles of neck, shoulders, back, hips, arms, and legs. "MyD88 was increased in the fibromyalgia mice’s DRGs compared with the normal group (Tukey’s test, * p < 0.05, n = 6)." (PMID 41008336, 2025). "The TLR4 and MyD88 levels increased upon fibromyalgia induction (Tukey’s test, * p < 0.05, n = 6), which was attenuated by the EA treatment and PD-L1 injection (Tukey’s test, # p < 0.05, n = 6)." (PMID 41008336, 2025). "In addition, the increased TLR4 and MyD88 concentrations in the SSCs of the fibromyalgia mice (Tukey’s test, * p < 0.05, n = 6) were inhibited by 2 Hz EA or PD-L1 injection (Tukey’s test, # p < 0.05, n = 6)." (PMID 41008336, 2025). "Our findings showed that EA and PD-L1 injection can mitigate mice fibromyalgia by decreasing TLR4 and downstream molecules such as MyD88, TRAF6, and pNF-κB." (PMID 41008336, 2025). "Regarding TLR4 cascades, our results indicated comparable changes in the TLR4, MyD88, and TRAF6 protein concentrations in the fibromyalgia mice with those in the normal mice (Tukey’s test, * p < 0.05, n = 6)." (PMID 41008336, 2025). "It was also reported that the activation of TLR4 by lysozyme induced TRIF but not MyD88 and further triggered weak inflammatory cytokine expression and augmented glutamate release, suggesting the existence of a MyD88-independent pathway for nociceptive progression in fibromyalgia." (PMID 41007675, 2025).
gastric adenocarcinoma (2 papers, 2016 to 2021). "Furthermore, we used The Cancer Genome Atlas (containing 220 gastric adenocarcinomas) to determine the amount of somatic variation in the MYD88 gene." (PMID 26700889, 2016).
gastric cardia carcinoma (2 papers, 2020 to 2023). A carcinoma that arises from epithelial cells of the cardia of stomach. "Gastric cardia cancer has the highest MyD88 expression and mainly in intestinal-type adenocarcinoma with inflammation." (PMID 32477927, 2020). "Gastric cardia cancer tumors with higher MyD88 expression had higher histological grade (p = 0.041)." (PMID 32477927, 2020). "Furthermore, strong expression of MYD88 from clinical samples of gastric cardia carcinoma supported our finding and suggested an oncogenic role of MYD88 in cancer." (PMID 37456890, 2023). "Correlation of MyD88 and NF-κB p50/105 expression in gastric cardia cancer tissue." (PMID 32477927, 2020).
hemophagocytic lymphohistiocytosis (2 papers, 2021 to 2025). "Diagnoses of early deceased patients with PIRD (n = 70 under 5 years of age) were mostly due to disorders with a high risk of hemophagocytic lymphohistiocytosis (81.4%); premature deaths in “innate” IEI were frequently due to IRAK4 or MyD88 deficiencies." (PMID 41347188, 2025). "The steep early decline in survival we observed in patients with disorders of immune regulation and innate IEI may argue for an extension of NBS to other immediately life-threatening IEI (e.g., familial hemophagocytic lymphohistiocytosis [FHL], XLP1, MyD88/IRAK4 deficiencies, and IPEX syndromes)." (PMID 41347188, 2025).
hemorrhage (2 papers, 2012 to 2013). Loss of blood from the vascular compartment to the exterior or into nonvascular body space as a result of rupture or severance of the blood vessels. "Subarachnoid hemorrhage was induced in TLR4−/−, TRIF−/−, MyD88−/− and wild type C57BL/6 mice by injecting 60 μl of autologous blood near the mesencephalon; animals were euthanized 1 to 15 days after SAH for immunohistochemical analysis to detect microglia or apoptotic cells." (PMID 23849248, 2013).